LEP (leptin)
Diseases named in the same sentence as LEP in open-access papers (continued):
Sharing a sentence is not in itself a finding about the gene and the disease.
anorexia nervosa (66 papers, 2009 to 2026). A disorder most often seen in adolescent females characterized by a refusal to maintain a minimally normal body weight, an intense fear of gaining weight, a disturbance in body image, and, in postmenarcheal females, the development of amenorrhea. "Low leptin levels in individuals with anorexia nervosa are associated with impaired skeletal maturation and growth failure, reduced peak bone mass, and low bone turnover." (PMID 40507931, 2025). "Mutations in the leptin gene can lead to specific leptin-deficient conditions such as lipodystrophy syndromes, hypothalamic amenorrhea, anorexia nervosa, and congenital leptin deficiency." (PMID 38707092, 2024). "A leptin analog, metreleptin, even exhibited swift antidepressant action in depressed anorexia-nervosa patients, which is associated with low leptin levels." (PMID 35633817, 2022). "Genetic correlations suggest a coexisting genetic predisposition to both low leptin levels and risk for anorexia nervosa (AN)." (PMID 34594363, 2021). "Leptin has an indispensable role in the weight loss related disorders like cachexia and anorexia nervosa, which has been associated with the low circulating plasma leptin levels." (PMID 29116252, 2017). "Leptin, a hormone secreted by adipose tissue, appears to play a major role in the homeostasis of body weight and psychobiological processes associated with anorexia nervosa (AN)." (PMID 28030575, 2016). "Extreme exercise (e.g., ballet dancers and gymnasts) and anorexia nervosa are associated with low gonadotropin and leptin levels." (PMID 22851226, 2013). "Moreover, anorexia nervosa is associated with changes in hormones with an impact on bone quality, including anorexigenic hormones such as leptin, peptide YY and GLP1." (PMID 39201093, 2024). "However, evidence in both rodent and human (patients with anorexia nervosa) studies led us to primarily discuss the potential causal role of low leptin levels in high PA." (PMID 35538440, 2022). "The hypothesis linking hyperactivity with weight loss associated hypoleptinemia in anorexia nervosa gained momentum after a study showing that leptin suppressed semi-starvation induced hyperactivity in rats." (PMID 32210308, 2020). "In addition, a clinical case review revealed longer survival in aggressive leptin-deficient women with anorexia nervosa." (PMID 28105927, 2016). "Moreover, leptin therapy for patients with very low leptin or leptin deficiency has proven to be relevant for diseases such as lipoatrophy, anorexia nervosa, hypothalamic amenorrhea, and some neuroendocrine disturbances." (PMID 25352831, 2014). "Another genetic finding approaching significance in anorexia nervosa involves a locus containing early B cell factor 1, which encodes a transcription factor important for immune system development, regulation of adipocyte/osteoblast differentiation and possible interaction with leptin signaling." (PMID 31717370, 2019). "Moreover, lower levels of LEP promoter methylation were associated with anorexia nervosa (AN)." (PMID 31878053, 2019). "This study aimed to provide a BMI‐adjusted meta‐analytical calculation of blood leptin levels across different eating disorders (EDs) including anorexia nervosa (AN), bulimia nervosa (BN), binge eating disorder (BED), recovered EDs, and healthy controls (HCs)." (PMID 39643920, 2025). "Leptin is an appetite-regulating adipokine that is reduced in patients with anorexia nervosa (AN), a psychiatric disorder characterized by self-imposed starvation, and has been linked to hyperactivity, a hallmark of AN." (PMID 38674862, 2024). "Hormones and neuroactive peptides have a significant impact on food reward circuits, and dysregulation in leptin or ghrelin functioning can alter eating behavior in anorexia nervosa and bulimia nervosa, according to data from basic research." (PMID 37404586, 2023). "In anorexia nervosa, extremely low leptin levels are found, corresponding to the almost completely depleted adipocytes." (PMID 37630700, 2023).
anorexia nervosa (continued). "In patients with anorexia nervosa, an eating disorder characterized by hypoleptinemia (serum leptin levels < 2 μg/l), hyperactivity of various degrees is frequent." (PMID 35538440, 2022). "The patients with anorexia nervosa are characterized by low levels of the satiety hormone leptin, whereas the hunger hormone ghrelin is elevated." (PMID 36545337, 2022). "In activity-based anorexia, which is considered a rat model of anorexia nervosa, leptin treatment also reduced running wheel activity." (PMID 35538440, 2022). "Patients with anorexia nervosa have significantly reduced serum leptin levels and free leptin index values, while soluble leptin receptor levels are significantly higher compared to those with normal body weight." (PMID 34579156, 2021). "Results of single SNP MR analyses and the overall causal effect of leptin levels (EWAS) on the risk for anorexia nervosa (AN) calculated using different MR methods." (PMID 34594363, 2021). "Multiple linear regression analysis with anorexia nervosa, bulimia nervosa and binge eating as dependent variables showed that IL-6 and leptin best explained ED symptoms, even when adjusted for body mass index (BMI)." (PMID 30873471, 2017). "By contrast, there was a close association between very low leptin levels and REE in severely underweight patients with anorexia nervosa; this association disappeared again during treatment, i.e. with increases in fat mass and plasma leptin concentrations." (PMID 27739007, 2016). "This is also supported by data from individuals with anorexia nervosa who have lowered serum leptin and T3, together with low fat mass." (PMID 28119632, 2016). "Anorexia nervosa (AN) presents an adaptive appetite regulating profile including high levels of ghrelin and 26RFa (orexigenic) and low levels of leptin and PYY (anorexigenic)." (PMID 25798605, 2015). "Chronic illness and anorexia nervosa with inducing hypothalamic amenorrhea can decrease serum leptin concentrations." (PMID 24639740, 2013). "Nutritional support to patients with anorexia nervosa improved percent body fat, BMI, leptin and gonadotropin secretion." (PMID 22851226, 2013). "Not only is plasma leptin increased in obese subjects, but leptin is decreased in adipose tissue mass induced by exercise and anorexia nervosa." (PMID 22481927, 2012). "Depressed sympathetic activity in anorexia nervosa may be attributed to abnormal glucose regulation and low leptin." (PMID 40422864, 2025). "The aim of this study was to assess whether circulating SIRT1 varies consistently with leptin, ghrelin, body mass index (BMI), and IgG reactive to hypothalamic antigens in anorexia nervosa (AN)." (PMID 37373917, 2023). "In addition, fasting during illness (or in anorexia nervosa) further downregulates TRH release through decreased leptin signalling." (PMID 33585976, 2021). "In this study, we focus on leptin levels in anorexia nervosa (AN)." (PMID 34594363, 2021). "Housing temperature plays a more critical role than leptin in the regulation of semi-starvation induced hyperactivity in rats, which may be of relevance for the management of hyperactivity in anorexia nervosa." (PMID 32210308, 2020). "Moreover, with weight restoration in patients with anorexia nervosa, leptin levels rise back to a normal range." (PMID 31717370, 2019). "Single nucleotide polymorphisms (SNPs) associated with leptin levels [unadjusted and adjusted for BMI, ng/ml (rank based inverse normal transformation)] derived by the EWAS and their association with the risk for anorexia nervosa (AN) (OR is transformed to beta)." (PMID 34594363, 2021). "Furthermore, serum leptin levels are known to be abnormally low in anorexia nervosa." (PMID 31717370, 2019). "Research has shown that the GH-IGF-1 axis, a major endocrine regulatory mechanism in anorexia nervosa, has IGF-1 levels that are proportional to leptin levels." (PMID 40161302, 2025).
anorexia nervosa (continued). "According to our previous study on leptin, plasma ADPN was measured in two age-matched cohorts consisting of 41 healthy subjects (HC) and 62 patients: thirty-four with a diagnosis of Anorexia Nervosa (AN), fourteen of Bulimia Nervosa (BN), and fourteen of Binge-Eating Disorder (BED)." (PMID 36674598, 2023). "On the other hand, activating CB1R by eCBs may, in turn, regulate leptin levels and signaling, as suggested previously in women with anorexia nervosa, whose AEA levels are elevated, whereas their leptin levels are reduced." (PMID 33210603, 2020). "Olanzapine treatment also reduced activity levels of patients with anorexia nervosa, without significant body weight and plasma leptin levels differences compared with untreated patients." (PMID 32528286, 2020). "Based on a PubMed search using the key words “Atypical Anorexia Nervosa” (or “Eating Disorder Not Otherwise Specified”) and leptin, we were able to identify a single study which included two patients with atypical AN, whose leptin concentrations were ≤ 1.92 ng/ml." (PMID 37874404, 2024).
osteoporosis (65 papers, 2010 to 2025). A condition of reduced bone mass, with decreased cortical thickness and a decrease in the number and size of the trabeculae of cancellous bone (but normal chemical composition), resulting in increased fracture incidence. "Cystic fibrosis patients have higher levels of leptin and are at a higher risk of developing osteopenia and osteoporosis through a multifactorial and yet not clearly understood mechanism." (PMID 40076690, 2025). "A deeper understanding of the interactions among muscle loss, fat accumulation, and leptin signaling is essential for addressing the multifactorial nature of sarcopenic obesity and its impact on osteoporosis." (PMID 40647619, 2025). "Another important clinical application of studying the correlation between leptin and bone density is predicting the risk of osteoporosis, especially postmenopausal osteoporotic fractures." (PMID 39165638, 2024). "An unfavorable profile was evidenced, according to which greater weight loss, sarcopenia, and osteoporosis were associated with lower leptin levels." (PMID 39599699, 2024). "Leptin or melatonin improved Sema4d's role in trabecular bone microstructure, bone production, and repairment of trabecular bone loss in osteoporosis rats." (PMID 37031174, 2023). "In conclusion, leptin and melatonin reversed the activation of osteoclasts caused by overexpression of Sema4D, which intensified the pathological process of osteoporosis." (PMID 37031174, 2023). "This study aimed to explore the relationships among leptin, sarcopenia, and osteoporosis in older adults, contributing to a more comprehensive understanding of their interconnected pathophysiology and informing future clinical interventions." (PMID 40647619, 2025). "This study aimed to investigate the relationships between leptin levels, skeletal muscle health, and osteoporosis in older women." (PMID 40647619, 2025). "Along these lines, patients with IBD and osteoporosis had lower leptin levels compared to normal BMD patients." (PMID 40076690, 2025). "Obese individuals release leptin from adipocytes, which, through a central regulatory mechanism involving the hypothalamus, inhibits bone formation, thereby contributing to osteoporosis." (PMID 41163684, 2025). "In contrast, a study showed that transplantation of mesenchymal stem cells overexpressing leptin facilitated regeneration of periodontal tissues in a rodent model of osteoporosis." (PMID 38753859, 2024). "Xi indicated that EGCG treatment significantly reduced serum calcium, urinary calcium, body weight, and body fat in mice with secondary osteoporosis, increases leptin levels, and significantly reduces alkaline phosphatase activity." (PMID 39027330, 2024). "Xi also indicated that EGCG treatment significantly reduces serum calcium, urinary calcium, body weight, and body fat in mice with secondary osteoporosis, and increases leptin levels." (PMID 39027330, 2024). "Higher serum leptin concentrations and a positive correlation with body mass index (BMI) have been confirmed in obese postmenopausal women with osteoporosis." (PMID 39165638, 2024). "The risk of fracture and osteoporosis appears to be increased in patients with OSAS, probably due to different mechanisms, such as hypoxia, OSAS-related respiratory acidosis, leptin, OSAS-related comorbidities and, of course, hypogonadism." (PMID 37881222, 2023). "MiR-29a in osteoblasts represses high-fat diet-mediated osteoporosis and body adiposis through targeting leptin." (PMID 36831000, 2023). "Leptin is involved in bone remodeling through direct or indirect means, acting on the development of bone diseases such as osteoporosis." (PMID 36670417, 2023). "Well-formed bone tissue emerged, indicating the potential applications of leptin, both for periodontal regeneration in patients with osteoporosis, and as a potential new treatment strategy for chronic periodontitis." (PMID 33967621, 2021).
osteoporosis (continued). "Leptin levels were inhibited, and urine Ca/Cr and calcium activity levels were increased in the model of osteoporosis, compared with the sham group." (PMID 31752063, 2020). "Rodent data and more importantly, successful small scaled trials for both hypothalamic amenorrhea and osteoporosis in young and lean females suggest that the risks inherent to treatment with leptin are manageable, if adequate safety precautions are met." (PMID 31156489, 2019). "The most common indicators associated with a clinical diagnosis of osteoporosis and follow-up observations were chosen, including ALP, OCN, calcitonin, parathyrin, and leptin." (PMID 30305826, 2018). "Since osteoporosis pathogenesis is strictly related with the metabolic status, the aim of this study is also to evaluate the role of sRAGE as marker of osteoporosis in correlation with BMI and the adipokines leptin, adiponectin and visfatin." (PMID 28630637, 2017). "There are shared multiple pathophysiological mechanisms for heart failure and osteoporosis, through HF neuroendocrine activation matrix protein abnormalities, parathyroid hormone, adiponectin and leptin, etc." (PMID 22957004, 2012). "In the future, further research on leptin and its receptors may provide potential therapeutic options for preventing and treating osteoporosis." (PMID 39165638, 2024). "Finally, the kinetics of Leptin and Osteopontin were opposite in the two forms of osteoporosis, with Leptin increasing in OVX and declining in HL-TS, and Osteopontin increasing in HL-TS but not in OVX." (PMID 36282293, 2023). "Using an OVX rat model, the current work intends to investigate the effects and processes of Sema4D, Sema4D paired with leptin, and Sema4D combined with melatonin on bone metabolism in an effort to identify possible molecular targets for osteoporosis therapeutic treatment." (PMID 37031174, 2023). "Meanwhile, many relevant biomarkers have shown the correlation between osteoporosis and already been used to auxiliary diagnose OP and assess bone metabolism, such as leptin, Interleukin-6 (IL-6), insulin-like growth factor 1 (IGF-1), and vascular endothelial growth factor (VEGF)." (PMID 35993023, 2022). "The role of leptin in osteoblasts differentiation and estrogens aromatization that takes place in adipocytes may protect people with a high BMI from osteoporosis." (PMID 36660085, 2022). "The plausible cause for this could be that in osteoporosis, the proinflammatory cytokines such as serum levels of IL-6, leptin, IL-1, and resistin increases and might be the main contributing factor in the pathogenesis of osteoporosis." (PMID 33519717, 2020). "Also, one recent study revealed that leptin played essential roles in several bone disorders including osteoporosis, fractures, osteoarthritis, and bone tumors." (PMID 32565794, 2020). "Leptin may be a target for the prevention and treatment of immobilization-induced osteoporosis and sarcopenia." (PMID 31648235, 2019). "Individuals with osteoporosis have reduced levels of leptin in the bone marrow microenvironment." (PMID 30715588, 2019). "The previous studies suggest that leptin, one of the remarkable adipokines, plays an essential role in osteogenesis and bone metabolism via multiple pathways and supports the possibility that leptin is involved in the onset or progression of various bone diseases, for example, osteoporosis." (PMID 26170530, 2015). "Previously, a number of human studies have suggested that adipokines, such as adiponectin, leptin, and resistin, might have a relationship with osteoporosis and BMD." (PMID 26170530, 2015). "However, the increase of peripheral levels can attenuate ovariectomy-induced osteoporosis in rats, suggesting the dual role of leptin and its receptors in regulating bone metabolism." (PMID 24250662, 2013). "The effect of propranolol on ovariectomy-induced osteoporosis could be exerted, at least partly, through the regulation of leptin signaling." (PMID 24250662, 2013).